CFTR (CF transmembrane conductance regulator)
Diseases named in the same sentence as CFTR in open-access papers (continued):
Sharing a sentence is not in itself a finding about the gene and the disease.
infection (286 papers, 2004 to 2026). The state of being infected such as from the introduction of a foreign agent such as serum, vaccine, antigenic substance or organism. "When the CFTR protein malfunctions, the resulting viscous, inspissated secretions cause blockage, infection, inflammation, and eventually organ destruction." (PMID 40804904, 2025). "One of the most important developments for CF patients at risk for Mab infection are new therapies like Trikafta (ETI) that manage the underlying defects caused by CFTR mutations." (PMID 40415550, 2025). "Patients with CF who are heterozygous carriers of CFTR gene mutations show clinical benefits, including improved infection survival." (PMID 40733537, 2025). "Although CFTR-deficient mouse models have been developed, they are more susceptible to infection, yet fail to exhibit the hallmark clinical manifestations of CF — viscous mucus obstructing the lungs, intestines, and other organs." (PMID 40705476, 2025). "Our data, however, suggest that CFTR loss per se in the lung augmented arachidonic acid uptake prior to inflammation or infection." (PMID 38743489, 2024). "CFTR mutations lead to an increased susceptibility to this mechanism, resulting in infection perpetuation in CF patients, whereas individuals with NCFB eliminate BCC infection more efficiently." (PMID 38762736, 2024). "The cystic fibrosis transmembrane conductance regulator (CFTR), a cAMP-dependent Cl− channel, is closely associated with multiple pathogen infections, such as SARS-CoV-2." (PMID 39205282, 2024). "Infection in the CF lung drives loss of lung function, and pulmonary LPS exposure in a CFTR knockout mouse model induced more extreme lung remodeling and increased pulmonary resistance compared to control mice." (PMID 37568151, 2023). "CFTR-deficient neutrophils poorly clear P. aeruginosa, leading to extended infection and greater mortality in mice." (PMID 36902441, 2023). "Studies of the neonatal CF pig (prior to the onset of infection and inflammation) have shown that loss of CFTR function leads to increased contractility in ASM." (PMID 37568151, 2023). "In order to evaluate CF lung context on Mabs infection, we next derived AOs from CF patients displaying Class I and II CFTR mutations." (PMID 37619220, 2023). "Mutations in the CFTR gene appear to make CF epithelial cells more susceptible to inflammation compared with healthy cells; for this reason, once an infection is introduced, it triggers the onset of mucosal damage and chronic airway infection." (PMID 36014562, 2022). "Despite the abundance of neutrophils, pwCF fail to successfully clear infection, demonstrating that mutations in the CFTR have direct consequences on host innate immune responses." (PMID 35408875, 2022). "Understanding the reciprocal interactions between CFTR and membrane lipids is important as membrane microdomains are implicated in the response to infection and airways host defense." (PMID 35060604, 2022). "The susceptibility to infection of polarized wild type and CFTR knockdown (CFTR-KD) airway epithelial cells was determined in the presence or absence of a healthy ASL or physiological saline." (PMID 35563895, 2022). "It is thus possible that a positive feedback loop ensues with worsening CFTR function caused by infection and neutrophil recruitment to the airways, leading to further infections." (PMID 35668512, 2022). "CFTR absence/dysfunction results in ion imbalance and airway surface dehydration that severely compromise the CF airway microenvironment, increasing infection susceptibility." (PMID 35406809, 2022). "Mutations in the CFTR gene produce an inherently proinflammatory cellular environment, in addition to repeated infections that set the stage for chronic airway infection and progressive loss of lung function." (PMID 36014562, 2022).
infection (continued). "Factors contributing to disease exacerbations and survival rate of CF patients are type of mutation in the CFTR gene, poor nutritional status, lung failure, and infection development by Pseudomonas aeruginosa." (PMID 34749804, 2021). "As the major channel mediating anion transport, the apically located CFTR was reportedly down-regulated after pathogenic infection in host epithelial cells." (PMID 33861752, 2021). "It was proposed that infection susceptibility in CF is correlated with lysosomal pH, and confirmed that in alveolar macrophages CFTR helps to maintain lysosomes at low pH, a phenomenon required for effective inhibition of bacteria growth." (PMID 34832033, 2021). "Despite this intense neutrophilic response, CF is characterized by an enhanced lung susceptibility to infections and a defective bacterial eradication due to dysfunctional CFTR protein." (PMID 34831067, 2021). "As evidenced by increased larval survival and reduced pathological signs, these findings indicate that CFTR-depleted fish are highly susceptible to GD01 infection and respond to phage treatment with Muddy." (PMID 34530447, 2021). "The infection is mainly associated with a genetic mutation in a protein namely cystic fibrosis transmembrane conductance regulator (CFTR)." (PMID 34630947, 2021). "Remarkably, this cooperative activity was retained in an M. abscessus model of infection in CFTR-depleted zebrafish, associated with a striking increase in larval survival and reduction in pathological signs." (PMID 34530447, 2021). "Surprisingly, CFTR KO was associated with decreased production of several inflammatory cytokines in response to infection." (PMID 32973772, 2020). "Treatment with roscovitine alone, roscovitine plus tezacaftor/ivacaftor, M3 alone or M3 plus tezacaftor/ivacaftor all were associated with a trend towards increased CFTR expression in CF MDMs during infection, but variability was noted within donors." (PMID 33303916, 2020). "Our study demonstrates that the defective response to infection in CF is related to a dysfunction in autophagy, inflammation resolution, and lipid metabolism, which are known to be caused by mutated CFTR." (PMID 32781626, 2020). "An intrinsic defect associated with CFTR deficiency is the susceptibility of CF airway cells to accumulate ROS, particularly during pathogen infection." (PMID 32849500, 2020). "Biallelic correction was demonstrated using improved transgenes for selection, but it required sequential infection with different HC-AdV targeting each CFTR allele, and a third step for SB-mediated elimination of the exogenous genes." (PMID 32455640, 2020). "Loss of CFTR increases susceptibility to infection through impaired NADPH oxidase-dependent restriction of intracellular growth and reduced neutrophil chemotaxis, which together compromise granuloma formation and integrity." (PMID 30759393, 2019). "bolletii, or M. chelonae led to increased susceptibility to infections and larval killing, similarly to Mabs-infected CFTR-defective animals." (PMID 30759393, 2019). "In CF patients who are unable to easily clear infection due to CFTR-deficient phagocytes against microorganisms, the increased lung inflammation and damage will contribute to a decline in pulmonary function." (PMID 31212791, 2019). "Infants with CFTR mutations show a peribronchial neutrophil infiltration prior to the establishment of infection in their lung." (PMID 30813645, 2019). "CFTR deficiency on epithelial cells drives alterations in airway biology that promote infection and ineffective airway clearance that lead to the progressive loss of lung function in patients with CF." (PMID 31262295, 2019). "The loss of a functional CFTR on the apical side of the respiratory epithelium causes an alteration of mucociliary clearance with opportunistic pathogen infections and chronic inflammation." (PMID 30581723, 2018).
infection (continued). "The Na+-NQR complex thus is able to power the infection of V. cholerae, not only leading to the release of K+ via osmotic imbalance caused by the CFTR (cystic fibrosis transmembrane conductance regulator) Cl- channel, but also the release of hemolysin." (PMID 29065131, 2017). "In our CF mouse model, we found that the CFTR deficiency was associated with a higher inflammatory response to P. aeruginosa at the early phases of infection which is in agreement with previous observations." (PMID 26883959, 2016). "Comparable results were obtained following infection of murine Mφ carrying the CFTRΔF508 mutation, representing the most frequent mutation encountered in CF patients and resulting in an abnormal CFTR protein." (PMID 27906132, 2016). "In our infection model, only the highly and intermediately mucoid type 3 strains caused more severe infections in CFTR–/– than in WT mice." (PMID 26469863, 2015). "This was associated with markedly elevated RSV titers within 48 h of infection in F508del CFTR cells relative to wt CFTR controls." (PMID 24056672, 2013). "A lower incidence of cellular apoptosis was noticed following infection of CFTR-deficient cells in vitro and following P. aerugonisa infection of mice which was improved with the addition of aSMase." (PMID 21490807, 2011). "Minimal CFTR function also associated with younger age of infection when 3 alternative definitions of infection with Pa, mucoid Pa or Asp were employed." (PMID 20932301, 2010). "Risk of infection is correlated with CFTR function for 8 of 9 organisms in patients with good lung function (>90%ile) but only 1 of 9 organisms in those with poorer lung function (<50%ile)." (PMID 20932301, 2010). "Two subsequent studies demonstrated that stratifying CFTR mutations by putative function was associated with lower rates of Pa infection." (PMID 20932301, 2010). "Mutations which permit residual CFTR function and confer a "mild" phenotypic effect have been associated with lower rates of Pa infection." (PMID 20932301, 2010). "Secondly, patient populations have been accrued to find genetic modifiers of traits such as risk of infection and quantifying the contribution CFTR has to infection aids the search for genetic modifiers of this trait providing novel therapeutic targets for CF." (PMID 20932301, 2010). "In conclusion, genotypes predicting 'Minimal' CFTR function are associated with increased risk and earlier age of infection by multiple organisms." (PMID 20932301, 2010). "Our study corroborates the finding that CFTR mutations which permit 'Residual" CFTR function (i.e. class IV or V mutations) are associated with reduced rates and delayed acquisition of Pa infection." (PMID 20932301, 2010). "CFTR mutations that permit 'Residual' function reduce the risk of infection with multiple organisms in patients with mild lung dysfunction evidenced by near normal forced expiratory volumes." (PMID 20932301, 2010). "Risk of infection is increased for 'Minimal' CFTR function using any definition of infection with Pseudomonas aeruginosa, mucoid Pseudomonas aeruginosa and Aspergillus fumigatus." (PMID 20932301, 2010). "Lung function affected the relationship of CFTR and infection risk and was retained as a significant covariate in all Cox regression models." (PMID 20932301, 2010). "Localization of CFTR to lipid rafts, cellular lipid membrane domains that are enriched cholesterol and sphingolipids, has been described following infection with P. aeruginosa, and has been linked to inflammatory signaling and apoptosis." (PMID 19344509, 2009). "In this study, we report that CFTR deficiency leads to increased alveolar macrophage death and persistent inflammation of the airways in pwCF, which is associated with impaired control of infection." (PMID 39903773, 2025).
infection (continued). "These include airway clearance, antibiotics for infections, pancreatic enzyme replacement and CFTR modulators that target specific mutations to improve CFTR function, such as ivacaftor (VX-770), lumacaftor (VX-809), tezacaftor (VX-661) and elexacaftor (VX-445)." (PMID 40573184, 2025). "CFTR mutations may also predispose pwCF to sterile inflammation and impair innate immune cell function, rendering them even more susceptible to infection." (PMID 39015565, 2024). "Additionally, there have been small incidences where P. aeruginosa is acquired after CFTR modulator commencement, suggesting that lung damage remains a risk factor for infection." (PMID 38442240, 2024). "Similarly, in the CF model in mice deficient in CFTR and infected with P. aeruginosa, aerosolized bLF restricted infection by reducing pulmonary bacterial load, inflammation and iron dysbalance." (PMID 37259341, 2023). "With CFTR modulator treatment, there are still knowledge gaps in understanding the host–microbial interactions and their impact on airway physiology, infection and the patient's susceptibility to infection." (PMID 36631132, 2023). "It is plausible to suggest that antibiotic treatment permeabilises the bacterial membrane, enabling the entry of CFTR modulators, where they can exert a direct antimicrobial effect potentially reducing pathogenic burden within CF airways and reducing infection." (PMID 35408875, 2022). "It remains unclear, however, whether the biophysical presence alone of an apical liquid is able to prevent bacteria-induced cytotoxicity during the infection of CFTR-deficient airway epithelial cells." (PMID 35563895, 2022). "It is also unknown whether the vector infection and the exogenous CFTR expression in this cell type will cause ciliopathies that impact its functions in MCC and normal innate immunity." (PMID 36304167, 2022). "However, there are knowledge gaps in how CFTR modulators impact airway physiology and infection and their ability to modulate the susceptibility to infection." (PMID 35408875, 2022). "Collectively, these studies highlight the importance of zebrafish infection models as excellent tools to decipher host–pathogen interactions and, for the first time, identified the pivotal role of CFTR in the immunological control of CF-associated NTM infections." (PMID 34530447, 2021). "It is still unknown whether inflammation is caused directly by the CFTR mutation or by the infection and mucus accumulation." (PMID 34832033, 2021). "We observe a nearly 50% loss in F508del-CFTR function after four hours of infection." (PMID 32092967, 2020). "Therefore, we studied peripheral-blood-derived monocytes from CF patients, bearing either homozygous or compound heterozygous ΔF508 mutation of CFTR, by in vitro infection with A. fumigatus." (PMID 32781626, 2020). "If the association among CFTR mutation and Mab infection is validated, indirectly, Trikafta could also protect CF patients from this pathogen." (PMID 31766758, 2019). "Although it is assumed that susceptibility to infections in CF results from defective mucociliary activity, CFTR dysfunction may also alter the inflammatory potential of innate immune cells, contributing to the infectious pathology in this disease." (PMID 30759393, 2019). "Given their capacity to promote phagolysosome maturation and ROS-mediated bactericidal response, we tested ABLs carrying PA, PI3P or PI5P on primary macrophages from healthy subjects with pharmacologically inhibited or genetically mutated CFTR after in vitro infection with PAO1." (PMID 28345623, 2017). "The infection of PA can secrete epoxide hydrolase, a kind of CF transmembrane conductance regulator (CFTR) inhibitor, which could cause neutrophil activation and tissue inflammation." (PMID 28589151, 2017).
infection (continued). "Although the detailed mechanisms of the high susceptibility of the CF lung to bacterial infections are not completely clear, increasing data are gradually revealing the properties of abnormal CFTR associated with the prevalent infection with P. aeruginosa and other pathogens." (PMID 27919253, 2016). "The exact molecular link between CFTR mutations and hypersensitivity to infections remains unclear and controversial." (PMID 25500839, 2014). "CFTR dysfunction in neutrophils compromises the phagocytic innate immunity, which may predispose CF lungs to infection." (PMID 25184794, 2014). "Without a more complete understanding of how defects in autophagy induced by mutations in CFTR impact S. aureus infection it is difficult to predict how pharmacological manipulation of the pathway might affect the course of infection." (PMID 24434788, 2014). "CFTR also plays key roles in the amplified response observed in secretory diarrheas, such as those elicited by cholera toxin during infection with Vibrio cholerae or by heat-stable enterotoxin during infection with pathogenic Escherichia coli." (PMID 24714160, 2014). "Cystic fibrosis transmembrane conductance regulator (CFTR) deficiency results in increases in lung ceramide levels due to alterations in lysosomal pH and is associated with augmentations in cell death, inflammation and infection susceptibility." (PMID 22849442, 2012). "To test whether expression of misfolded ΔF508 CFTR renders cells more susceptible to infection due to an increase in cell surface attachment of virus particles, we performed a binding assay with AAV2 on these cell lines." (PMID 21625534, 2011). "It remains also unclear whether COX-2 up-regulation observed in polyps from CF patients is a direct consequence of CFTR mutation and/or a secondary consequence of airway inflammation and infection inherent to CF disease." (PMID 20429932, 2010). "Finally, neonatal CF pigs show acquisition of infection with a variety of organisms indicating that loss of CFTR function causes a pervasive defect in lung defense." (PMID 20932301, 2010). "However, at the lowest lung function strata (<50th %ile), CFTR genotype significantly alters infection risk with only 1 organism (Sa)." (PMID 20932301, 2010). "Whether CFTR dysfunction results directly in an increased predisposition to infection and whether inflammation arises independently from infection remains to be established." (PMID 17064416, 2006). "Furthermore, understanding how CFTR modulators modulate immune responses—both in the lungs and systemically—is vital, as these changes may impact susceptibility to infection, inflammatory status, and even tumorigenesis." (PMID 41154689, 2025). "Thus, S1 spike protein, the part of the SARS-CoV-2 virus that directly contacts ACE2 in target tissues, and that induces loss of CFTR, may remain in production and distribution to the rest of the body long after the active infection phase has terminated." (PMID 39043712, 2024). "One additional confounder when considering the role of macrophages in chronic P. aeruginosa infection within the specific context of CF, is the controversy over whether CFTR defects result in intrinsic macrophage defects that predispose these patients to infection." (PMID 39015565, 2024). "In particular, CFTR deficiency leads to dehydrated, nutrient-rich mucus which creates a proper milieu for pathogenicity and colonisation by opportunistic organisms, which leads to a chronic inflammatory environment and susceptibility for infection ultimately leading to airway damage." (PMID 39595943, 2024). "Mutations in the CFTR gene, resulting in decreased CFTR activity, cause impairments in the hydration of the airway’s epithelial surface with highly viscous mucus, which limits mucociliary clearance in the airways, leading to the infection and inflammation of airway tissues." (PMID 34573044, 2021).